OGT (O-linked N-acetylglucosamine (GlcNAc) transferase)
Diseases named in the same sentence as OGT in open-access papers (continued):
Sharing a sentence is not in itself a finding about the gene and the disease.
Hyperglycemia (continued). "Here, we conclusively demonstrated in TNBC model systems that OGT was an upstream regulator of this CSC pathway in a catalytic fashion; was itself regulated by splicing factors in this tumorigenic pathway; and that a key hallmark of metabolic disease, hyperglycemia, further activated this pathway." (PMID 37231419, 2023). "Using an in vivo rat model of maternal hyperglycemia, we show similarly elevated O-GlcNAc levels and epigenetic dysregulations in the developing embryo brains because of hyperglycemia, whereas pharmacological inhibition of O-GlcNAc transferase (OGT) restored these molecular changes." (PMID 35470239, 2022). "Based on OGT siRNA data, the ability of miR-200a/200b mimics to downregulate OGT expression and O-GlcNAcylation levels may act as a possible mechanism to attenuate hyperglycemia-induced endothelial inflammation by regulating nuclear factor-kB activity." (PMID 29720943, 2018). "OGT and O-GlcNAc protein expression were upregulated in the aortic vessels of smOGTWT mice following STZ-induced hyperglycemia." (PMID 37175604, 2023). "Our data underscores a conceptual link between OGT-mediated O-GlcNAcylation and SMC de-differentiation and highlights smooth muscle OGT as a putative target of hyperglycemia-induced vasculopathy." (PMID 37175604, 2023). "Interestingly, the protein levels of H3K4 methyltransferase, Mll1 were up-regulated due to hyperglycemia in embryo brains and treatment with OGT inhibitor restored Mll1 to normal levels, suggesting that this increased Mll1 could have resulted in H3K4me3 enrichment on the affected gene promoters." (PMID 35470239, 2022). "Hyperglycemia is only one aspect of metabolic disease, so a more in-depth study of OGT-CSC pathway is needed using in vivo models that incorporate stable knockdown OGT/TNBC lines and/or OGT inhibitors with enhanced in vivo activity." (PMID 37231419, 2023). "Although earlier work has reported that OGT-mediated O-GlcNAcylation promotes diabetic vascular calcification, the conceptual link between SMC-derived OGT and hyperglycemia-driven lesion pathogenesis has not been previously explored." (PMID 37175604, 2023). "Studies in diabetes mellitus have shown that hyperglycemia directly increases protein O-GlcNAcylation, at least in part, by increasing the glucose flux through HBP, and that OGT/OGA expression may be regulated by chronic hyperglycemia." (PMID 34140929, 2021). "Inhibition of OGT blocked the negative impact of hyperglycemia or glucosamine supplementation on blastocyst formation, cell number, and apoptosis during mouse embryogenesis." (PMID 33610549, 2021). "During hyperglycemia with activation of the HBP, OGT and OGA expression may be upregulated to manage the increase in the level of UDP-GlcNAc." (PMID 23734074, 2013). "Interestingly, in the aortic vasculature of STZ-treated smOGTKO mice, hyperglycemia failed to further increase the residual OGT and O-GlcNAc protein expression." (PMID 37175604, 2023). "Placental OGT and OGA expression levels both affect placental development; however, maternal stress seems to be the pivotal regulator of OGT and is more critical for fetal neurodevelopment, rather than hyperglycemia." (PMID 34140929, 2021).
colorectal cancer (20 papers, 2014 to 2025). A primary or metastatic malignant neoplasm that affects the colon or rectum. "We found that deletion of OGT (Ogt−/−) caused a marked reduction in tumor growth in both syngeneic tumor models and a genetic colorectal cancer (CRC) model induced by mutation of the Apc gene (Apcmin)." (PMID 38168435, 2024). "We found that deletion of OGT (Ogt-/-) caused a marked reduction in tumor growth in both syngeneic mice tumor models and a genetic mice colorectal cancer (CRC) model induced by mutation of the Apc gene (Apcmin)." (PMID 39365288, 2024). "Kaplan-Meier analysis revealed that elevated OGT expression were associated with poor survival of patients with colorectal cancer and liver hepatocellular carcinoma." (PMID 38778217, 2024). "The carcinogenic effect of OGT is closely associated with its role in driving cell growth in various malignancies, such as liver cancer, gastric cancer (GC), and colorectal cancer (CRC)." (PMID 39285476, 2024). "In two independent microarray data sets, the expression of OGA and OGT was significantly associated with poor cancer-specific survival of colorectal cancer (CRC) patients." (PMID 25000257, 2014). "We propose that the OGT–YTHDF1–c-Myc axis underlies colorectal cancer tumorigenesis." (PMID 37086786, 2023). "To determine the effects of His-901 and Asp-925 mutations in the OGT protein and kaempferol treatment on OGT enzymatic activity in HCT116 colorectal cancer cells, we employed the UDP-GloTM glycosyltransferase assay kit." (PMID 40959291, 2025). "Elevated OGT expression and increased cellular O-GlcNAcylation have been observed in many cancer types including prostate, breast and colorectal cancer." (PMID 39413067, 2024). "To further investigate the function of OGT in colorectal cancer, we performed western blotting and immunohistochemistry (IHC) analyses of OGT expression in 30 pairs of human colorectal cancer tissues and matching peritumoral tissues." (PMID 38778217, 2024). "Together, these results demonstrated that OGT expression is crucial for colorectal cancer cell proliferation and tumor growth." (PMID 38778217, 2024). "Consistently, both mRNA and protein levels of OGT were significantly increased in a panel of colorectal cancer cell lines (HCT116, HT-29, RKO, SW620, LoVo) compared to a normal colon epithethial cell NCM460." (PMID 38778217, 2024). "OGT expression was significantly upregulated in colorectal cancer (CRC), stomach adenocarcinoma (STAD), lung adenocarcinoma (LUAD), liver hepatocellular carcinoma (LIHC) and prostate adenocarcinoma (PRED) tissues compared to the adjacent normal tissues." (PMID 38778217, 2024). "Collectively, these results support the cellular data, and underscore the importance of the OGT–c-Myc–PDK2 axis in colorectal cancer development." (PMID 38778217, 2024). "Together, OGT depletion caused a downregulation of glycolysis, but upregulation of the TCA cycle in colorectal cancer cells." (PMID 38778217, 2024). "Our findings reveal that the OGT–c-Myc–PDK2 axis plays a key role in regulating glucose metabolism in colorectal cancer, and suggest new therapeutic strategies." (PMID 38778217, 2024). "This study highlights the OGT–c-Myc–PDK2 axis as a key mechanism linking oncoprotein activation with deregulated glucose metabolism in colorectal cancer." (PMID 38778217, 2024). "In colorectal cancer, levels of OGT and O-GlcNAc are significantly higher in lymph node metastases when compared to primary tumors." (PMID 37838167, 2023). "Genetic inhibition of OGT in colorectal cancer cells reduces phosphorylation of Akt and mTOR, thus impairing cancer cell proliferation." (PMID 37838167, 2023). "In colorectal cancer, pharmacological inhibition of OGT reduces the activity of β-catenin and reduces cell proliferation." (PMID 37838167, 2023). "In contrast, overexpression of OGT increases phosphorylation and activity of Akt and mTOR, which in turn enhances the proliferation and metastasis ability of colorectal cancer cells." (PMID 37838167, 2023).
colorectal cancer (continued). "Increased O-GlcNAc level reduces the level of E-cadherin in colorectal cancer cells, while inhibition of OGT results in an increased level of E-cadherin." (PMID 37838167, 2023). "In colorectal cancer, OGT and O-GlcNAc activate the Akt/mTOR signaling pathway to control tumor progression." (PMID 37838167, 2023). "This study identified XIAP as another E3 ubiquitin ligase of OGT in HCT116 human colorectal carcinoma cells." (PMID 32994395, 2020). "We overexpressed DDX5 or added an mTOR agonist (MHY1485) in the OGT knockdown colorectal cancer cell line." (PMID 30484950, 2019). "Meta-analysis of breast and colorectal cancers revealed positive correlations in the relative protein abundance of OGT and proteasome subunits." (PMID 29941490, 2018). "Meta-analysis of The Cancer Genome Atlas (TCGA) data sets of breast and colorectal cancers revealed positive correlations in protein abundance between OGT and proteasome subunits." (PMID 29941490, 2018). "An independent cohort of colorectal cancer patients from the Moffitt Cancer Center (GSE17536) also showed that patients with high levels of OGT exhibited worse prognoses." (PMID 27542217, 2016). "Thus, our study identifies OGT–c-Myc–PDK2 axis as a key mechanism to regulate colorectal cancer metabolism." (PMID 38778217, 2024). "Additionally, microRNA-101-regulated OGT was found to promote EZH2 protein stability in colorectal cancer." (PMID 34462420, 2021). "Similarly, we knocked down DDX5 on the basis of OGT overexpression or used the mTOR inhibitor (Rapamycin) significantly reduce the proliferation and metastasis of colorectal cancer cells." (PMID 30484950, 2019). "Our results indicate that OGT can directly interact with DDX5 in colorectal cancer cell lines." (PMID 30484950, 2019). "This scenario may explain the strong positive correlations between protein abundances of OGT and most of the proteasome subunits in breast and colorectal cancers." (PMID 29941490, 2018). "In addition, loss of OGT reduced the production of lactate, NADPH and GSH, which were fully rescued by reconstituted expression of c-Myc, suggesting that OGT-mediated regulation of glucose metabolism in colorectal cancer cells is mainly dependent on c-Myc." (PMID 38778217, 2024). "This study reveals that kaempferol suppresses colorectal cancer progression by dual targeting of glucose metabolism (reducing UDP-GlcNAc flux) and OGT activity, thereby diminishing O-GlcNAcylation of Hsp47." (PMID 40959291, 2025). "Depletion of OGT, the sole transferase of O-GlcNAc, significantly increases the TCA cycle metabolism in colorectal cancer cells." (PMID 38778217, 2024). "Accumulation of β-catenin in the nucleus promotes the expression of glutamine transporters to enhance glutamine uptake in colorectal cancer cells in a CEMIP and OGT-dependent manner." (PMID 37838167, 2023). "We confirmed this result by inhibiting OGT and/or EZH2: respectively with Ac5S-GlcNAc (Ac5S) and GSK343 specific inhibitors and validated them also in LS174T human colorectal cancer cell line." (PMID 33126652, 2020). "Taken together, these results indicated that OGT‐mediated O‐GlcNAcylation stabilizes DDX5, promoting activation of the AKT/mTOR signalling pathway, thus accelerating colorectal cancer progression." (PMID 30484950, 2019). "We examined the expression of OGT, DDX5, and O‐GlcNAcylation in four colorectal cancer cell lines (HT29, HCT116, SW480, SW620) and the normal human intestinal epithelial cell line NCM460." (PMID 30484950, 2019). "As a previous study reported that NONO interacts with OGT in HCT116 human colorectal carcinoma cells, further experiments were conducted using this cell line." (PMID 40360465, 2025). "In this study, we characterized eight colorectal cancer cell lines and one non-cancerous cell line for O-GlcNAc-related profiles such as the expression of OGT, OGA, and total protein O-GlcNAcylation, along with their sensitivity toward OSMI-1 (Os), an OGT inhibitor (OGTi)." (PMID 39413067, 2024).
congenital disorder of glycosylation (17 papers, 2020 to 2026). Congenital disorder of glycosylation (CDG) is a fast growing group of inborn errors of metabolism characterized by defective activity of enzymes that participate in glycosylation (modification of proteins and other macromolecules by adding and processing of oligosaccharide side chains). "Missense variants in O-GlcNAc transferase (OGT) result in OGT congenital disorder of glycosylation (OGT-CDG), an intellectual disability syndrome associated with O-GlcNAc dyshomeostasis and a range of neurodevelopmental defects." (PMID 42209020, 2026). "Recently, missense variants in OGT have been reported in patients with a novel, syndromic form of X-linked intellectual disability (ID), called the OGT-linked congenital disorder of glycosylation (OGT-CDG)." (PMID 39706180, 2025). "To date, nine variants of OGT that segregate with OGT Congenital Disorder of Glycosylation (OGT-CDG) have been reported and characterized." (PMID 39059494, 2024). "Missense variants of OGT have recently been shown to segregate with an X-linked syndromic form of intellectual disability, OGT-linked congenital disorder of glycosylation (OGT-CDG)." (PMID 38566589, 2024). "Recently, mutations in the X chromosome gene OGT were identified as causal for ID, a condition termed OGT congenital disorder of glycosylation (OGT-CDG)." (PMID 39535175, 2024). "Recently, missense variants of OGT have been identified in individuals affected by ID, giving rise to a syndrome named OGT-linked congenital disorder of glycosylation (OGT-CDG)." (PMID 38566589, 2024). "Inborn OGT genetic variants were recently shown to mediate a novel type of congenital disorder of glycosylation (OGT-CDG), which is characterised by X-linked intellectual disability (XLID) and developmental delay." (PMID 37334838, 2023). "Missense mutations in OGT have been associated with developmental disorders, OGT‐linked congenital disorder of glycosylation (OGT‐CDG), which are characterized by intellectual disability." (PMID 33098688, 2021). "The disorder, termed OGT-linked congenital disorder of glycosylation (OGT-CDG), presents with a range of clinical signs beyond ID that are generally indicative of broad developmental defects, including clinodactyly (curved fingers), short stature and facial dysmorphisms." (PMID 36924340, 2023). "Phenotypic characterization of several OGT variants gave rise to a new syndrome of congenital disorder of glycosylation named OGT-CDG; however, the mechanisms underlying the patient brain phenotypes remain unknown." (PMID 33610549, 2021). "Recently, dysregulation of O‐GlcNAcylation caused by OGT gene mutations has been associated with a developmental disorder termed OGT‐linked congenital disorder of glycosylation (OGT‐CDG) with patients characterized by intellectual disability and developmental delay." (PMID 33098688, 2021). "Hypomorphic mutations of OGT are implicated in an X-linked intellectual disability syndrome, a severe neurodevelopmental disorder now termed OGT-associated Congenital Disorder of Glycosylation (OGT-CDG)." (PMID 38619103, 2024). "Mutations in OGT have recently been discovered to cause a novel Congenital Disorder of Glycosylation (OGT-CDG) that is characterized by intellectual disability." (PMID 35500025, 2022). "Missense mutations in OGT segregate with a novel X-linked intellectual disability syndrome, the OGT congenital disorder of glycosylation (OGT-CDG)." (PMID 35863433, 2022). "Missense variants in OGT are linked to a novel intellectual disability syndrome known as OGT congenital disorder of glycosylation (OGT-CDG)." (PMID 39706180, 2025). "Variants in the human β-N-acetylglucosamine (O-GlcNAc) transferase (OGT) gene give rise to an intellectual disability (ID) syndrome termed OGT congenital disorder of glycosylation (OGT-CDG)." (PMID 41033462, 2025).
congenital disorder of glycosylation (continued). "Pathogenic missense variants in O-GlcNAc transferase (OGT) give rise to OGT congenital disorder of glycosylation (OGT-CDG), a rare, clinically heterogenous intellectual disability (ID) syndrome where the underlying molecular etiology is unknown." (PMID 35863433, 2022). "In this review, we compile the work from the last few years that clearly delineates a new syndromic form of ID, which we propose to classify as a novel Congenital Disorder of Glycosylation (OGT-CDG)." (PMID 32080367, 2020). "Interestingly, missense variants in OGT also give rise to an intellectual disability syndrome called the O-GlcNAc Transferase Congenital Disorder of Glycosylation (OGT-CDG)." (PMID 40592469, 2025). "Recently, variants in OGT have been associated with a new syndromic form of intellectual disability, termed OGT Congenital Disorder of Glycosylation (OGT-CDG)." (PMID 41033462, 2025). "On the basis of the common features of these patients and the fact that the clinical features co-segregate with the OGT gene it has been proposed that this syndrome be classified as a congenital disorder of glycosylation (CDG) termed OGT-CDG." (PMID 33329753, 2020).